SPDYE5 (speedy/RINGO cell cycle regulator family member E5)
Tractability: No criterion of Open Targets' tractability assessment is met for any kind of drug.
Gene: Protein-coding gene on chromosome 7 (75,492,320 to 75,504,316, forward strand). Ensembl gene ENSG00000170092.
Gene Ontology:
Molecular function: protein kinase binding
Genetic constraint (gnomAD): Loss-of-function variants: 15 observed, 35.14 expected, observed/expected ratio (o/e) 0.43, 90% interval 0.28 to 0.66. The upper end of that interval is the gene's LOEUF score, 0.66, which puts it in group 2 of 6, group 1 being the genes least tolerant of losing a copy. Missense variants: 322 observed, 407.66 expected, observed/expected ratio (o/e) 0.79, 90% interval 0.72 to 0.87. Synonymous variants: 115 observed, 147.79 expected, observed/expected ratio (o/e) 0.78, 90% interval 0.67 to 0.91.
Homologues: Orthologues: mouse Spdye4a (33% identical), rat Spdye4 (33% identical), mouse Spdye4b (29% identical). Paralogues in human: SPDYE2 (96% identical), SPDYE2B (96% identical), SPDYE6 (96% identical), SPDYE21 (95% identical), SPDYE1 (88% identical), SPDYE18 (82% identical), SPDYE16 (82% identical), SPDYE3 (62% identical), SPDYE12 (55% identical), SPDYE13 (55% identical), SPDYE14 (55% identical), SPDYE15 (55% identical), and 6 more.